SOX2 (SRY-box transcription factor 2)
Diseases named in the same sentence as SOX2 in open-access papers (continued):
Sharing a sentence is not in itself a finding about the gene and the disease.
glioma (continued). "The role of SOX2 in promoting cancer cell characteristics is well-established, and its expression in gliomas is known to correlate positively with the grade of malignancy." (PMID 41458623, 2025). "For instance, SOX2 can upregulate the expression of genes such as Cyclin D1 and c-Myc to promote glioma cell proliferation." (PMID 39781344, 2025). "Clusters with high entropy were further validated to exhibit the elevated expression of canonical glioma stem-like cell markers (SOX2, OLIG2, PROM1), supporting their classification as high-stemness populations beyond theoretical entropy alone." (PMID 40806540, 2025). "It phosphorylates the Ser251 of human SOX2 to prevent WWP2-mediated ubiquitination, thereby stabilizing the SOX2 protein and promoting glioma stem cell (GSC) maintenance under normal circumstances." (PMID 40038612, 2025). "The preprint primarily established a unidirectional ZFHX4-AS1 → ZFHX4 → SOX2 axis that promotes glioma cell proliferation, migration, and invasion, supported by correlation and rescue assays." (PMID 41458623, 2025). "For example, SOX2 has emerged as a potential marker for transformed glioma cells, as its high expression is consistently observed in high-grade glioma cells." (PMID 40149830, 2025). "In this study, we identify a novel long noncoding RNA (lncRNA), cancer stem cell‐associated distal enhancer of SOX2 (CASCADES), that functions as an epigenetic regulator in glioma CSCs (GSCs)." (PMID 39323013, 2025). "Based on the results of the RT-PCR, SOX2 is highly expressed in glioma tissues, and its expression increases with tumor grade." (PMID 41458623, 2025). "Gliomas, similar to neural stem cells, exhibit an accessible chromatin state at the SOX2 enhancer cluster, which contributes to its sustained high expression and drives tumor cell proliferation." (PMID 41426972, 2025). "The knockdown of SOX2 significantly reduced glioma cell migration and invasion in wound healing assays, transwell assays." (PMID 41458623, 2025). "Similar to our findings, ITGA2 has been shown to be enriched in glioma stem cells and co-expressed with the stem cell marker SOX2." (PMID 40316546, 2025). "IHC glioma marker panel (SOX2, Tubulin, beta-3, EGFR, A2B5, and c-MET).FISH used to determine EGFR gene amplification in CTCs from known amplified cases." (PMID 38481938, 2024). "The goal of this study is to identify the mechanisms activated by Oct4 and Sox2 reprogramming transcription factors that drive glioma-propagating stem cells and determine their potential as targets for developing novel anti-cancer therapeutics." (PMID 39796709, 2024). "An in vitro study with the U87 glioma cell line demonstrated that transfection of glioma cells with the miRNA miR-378 led to increased expression of SOX2, the stem cell surface marker CD133, and induction of stem cell properties." (PMID 39095874, 2024). "This study elucidates Shikonin's capacity to effectively induce necroptosis in glioma cells, concurrently mitigating glioma stemness, as evidenced by diminished levels of stem cell markers, namely SOX2, CD44, CHI3L1, and CD24." (PMID 39619148, 2024). "The outcome of HIF1α/HIF2α-Sox2 signaling in a hypoxic microenvironment is the dedifferentiation of differentiated glioma cells leading to the formation of glioma stem cells." (PMID 38672638, 2024). "SRY-box transcription factor 2 (SOX2), epidermal growth factor receptor (EGFR), and Myc proto-oncogene (MYC) are genes whose upregulation is associated with glioma stemness." (PMID 39419964, 2024). "In a hypoxic microenvironment, the HIF1α/HIF2α-Sox2 network induced the formation of GSCs by dedifferentiating differentiated glioma cells, thereby promoting chemoresistance of the glioma cells." (PMID 38794149, 2024). "SOX2, a well-established marker of glioma stemness, was found to be slightly elevated in the middle stage and significantly down-regulated in the terminal stages." (PMID 39033204, 2024).
glioma (continued). "The values of SOX2 across all steps suggest some stemness, either glioma stem cells or more likely tumor cells with stem cell phenotype considering low expression of SOX10 and NESTIN." (PMID 39230703, 2024). "In vivo, glioma stem cells (GSCs) with tumor self-renewal ability and aggressive growth metastasis are typically found in the perivascular niche, expressing SOX2, OLIG2, and NESTIN." (PMID 38390494, 2024). "Another study also showed that circPTN promotes glioma growth and stemness by sponging miR-145-5p and miR-330-5p, this results in increased expression of NES, CD133, SOX9 and SOX2, which promotes self-renewal of glioma stem cells and regulates gliomagenesis." (PMID 39698112, 2024). "We found HML-2 expression in the same cells and tissues that expressed stem cell markers, namely OCT4, Nestin, Vimentin, and Sox2 in patients with high-grade glioma." (PMID 37395282, 2023). "The expression profiles of CD133, CD44, Nestin, SOX2, Nanog, ALDH1A3 and OCT4, which are associated with glioma stem cell (GSC) signatures, were visualized in a heatmap." (PMID 36755314, 2023). "Sox2 was identified as a novel antigen in glioma, and targeting a Sox2 vaccine successfully improved glioma T-cell-based immunotherapy." (PMID 37251931, 2023). "SOX9, a player in CSC sustenance, is also responsible for cell senescence in gliomas and works synergistically with SOX2." (PMID 36834653, 2023). "Because the glioma stem cell niche is associated with overexpression of several proteins, including OCT4, Nestin, Vimentin, and Sox-2, we sought to visualize HML-2 expression in situ with multiplex immunofluorescence." (PMID 37395282, 2023). "Here we have identified SOX2, a marker of glioma stem cells (GSCs), as a key determinant of HCMV gene expression in gliomas." (PMID 37058447, 2023). "For example, ID4 enhances SOX2 protein expression by inhibiting miR‐9*, thereby conferring stemness and chemotherapy resistance to glioma cells and GSCs." (PMID 37576862, 2023). "We also conducted immunofluorescence staining for glial markers GFAP, glioma stem cell markers SOX2, tumor proliferation marker Ki-67 and invasion markers Vimentin." (PMID 37891669, 2023). "In gliomas, SOX2 expression strengthens migration and invasion, and is positively correlated with malignancy grade." (PMID 37147666, 2023). "The positive feedback loop of GSCAR/DHX9-IGF2BP2/SOX2 distinguishes glioma stem cells from other glioma tumor cells regulated by the GSCAR/miR-6760-5p/ SRSF1 axis." (PMID 37063420, 2023). "Glioma stem cells, defined by SOX2 expression, appear to preferentially display primary cilia with activated hedgehog signaling." (PMID 37830570, 2023). "This expression pattern of SOX2 mirrored that of IE1 in gliomas (also corroborated by pp65 staining in S14 Fig), and linear regression analysis showed a strong positive correlation between IE1 and SOX2 expression in a cohort of 178 HGG patients." (PMID 37058447, 2023). "Specifically, the expression of SOX2 identifies glioma stem-like cells, contributing to our understanding of tumor-initiating and maintenance capabilities within the broader glioblastoma microenvironment." (PMID 38274817, 2023). "NEAT1 promotes glioma development by upregulating SOX2 expression through the suppression of miR-132." (PMID 37403043, 2023). "Consistent with former findings 51, SOX2 was verified to be highly expressed in gliomas, which correlates with worse clinical outcomes." (PMID 37063420, 2023). "On the other hand, rapamycin attenuated the production of SOX protein, and it was found that combining rapamycin and temozolomide suppressed the progression of glioma in cells that expressed high levels of SOX2/SOX9." (PMID 37183261, 2023). "SOX4 forms a complex of transcripts with OCT‐4 protein that triggers SOX2 expression and enhances the carcinogenicity of glioma cells." (PMID 36987665, 2023).
glioma (continued). "An increase of SOX21 in glioma cells reduced tumor size and inhibited glioma progression in vivo by forming complexes with SOX2 protein, therefore changing the balance between these proteins in the tumor." (PMID 37047365, 2023). "Since IE1 expression in gliomas has previously been positively correlated with tumor grades, we reasoned that if SOX2 determines HCMV infection in gliomas, the SOX2 expression pattern in gliomas should mirror that of IE1." (PMID 37058447, 2023). "While Clusters A and B resemble normal and reactive brain tissue, the SOX2 and Ki67 labeling indices indicate that these clusters comprise samples with variable levels of glioma infiltration." (PMID 37142563, 2023). "HIF1α/HIF2α induce the dedifferentiation of glioma cells into CSCs through SOX2 under hypoxic conditions, thereby promoting chemoresistance of glioma cells." (PMID 37576862, 2023). "Our analysis of tumor tissue in patients with gliomas shows that SOX2 expression level can be positively correlated with HCMV IE1 levels and the grade of glioma." (PMID 37058447, 2023). "Like what was observedin the context of CRC, METTL3 was foundto target SOX2 and consequently support the maintenance of highlytumorigenic glioma stem-like cells (GSCs) and the de-differentiationof glioma cells." (PMID 36692498, 2023). "A rise in miR-21-5p was observed to increase the migration and invasion potential of glioma cells via increasing SOX2 expression." (PMID 36649032, 2023). "Together, these data demonstrate that high levels of both SOX2 and IE1 in gliomas are associated with a poor prognosis for patients with glioma." (PMID 37058447, 2023). "In this study, we first show, to our knowledge, that SOX2 is crucial for HCMV infection in glioma cells." (PMID 37058447, 2023). "Immunohistochemistry revealed cytoplasmic (P)RR expression and nuclear SOX2 expression in human glioma tissues." (PMID 36646875, 2023). "For example, it has been demonstrated that lncRNA MALAT1 promotes the expression of SRY-box transcription factor 2 (SOX2) by suppressing miR-129 to promote glioma stem cell viability, proliferative abilities, and tumorigenesis." (PMID 36819921, 2023). "In 15 IDH-wild-type gliomas analyzed, malignant cells uniformly expressed SOX2 and harbored chromosome 7gain/chromosome 10loss." (PMID 37055795, 2023). "Among the analyzed tumors, GBM8 exhibited the highest proportion of SOX2+ glioma stem-like cells, followed by GBM18 and GBM31R." (PMID 38274817, 2023). "ANGPTL4 overexpression can lead to the enrichment of glioma stem-like cells (GSCs), which is distinguished by the level of polycomb complex protein BMI-1 and SOX2." (PMID 36247876, 2022). "The analysis shows that Notch1 and Sox2 have a positive feedback regulation mechanism, and Notch4 predicts the malignant degree of glioma." (PMID 35935338, 2022). "F2R promotes glioma cell proliferation and metastasis under SOX2 and actives the WNT/β-catenin signaling pathway." (PMID 36245971, 2022). "Previous work showed that the expression of OCT4, SOX2 and Nanog correlated positively with tumour malignancy in human gliomas." (PMID 35419917, 2022). "Then, sphere formation by single glioma cells was detected, and we found decreased sphere formation after Sox2 knockout." (PMID 34976166, 2022). "For example, NEAT1 knockdown suppressed the metastatic ability of glioma by upregulating SRY-Box transcription factor 2 (SOX2) repression by miR-132." (PMID 35030969, 2022). "In fact, over time in slice culture we would expect SOX2+ glioma cells to outgrow the differentiated myeloid fraction, and perhaps become more susceptible to Zika, yet within the timeframe of our experiments (up to 7 days) we did not observe such a tendency." (PMID 36174572, 2022).
glioma (continued). "This study demonstrates that both HIF1α and HIF2α, as genes upstream of Sox2, regulate the malignant progression of glioma through dedifferentiation." (PMID 34976166, 2022). "Pediatric non-cycling PROM1+ cells were further classified according to the expression of other putative glioma stem cells marker such as SOX2 and OLIG2: 54% expressed both markers, 32% only SOX2, 6% only OLIG2, and 8% neither (right)." (PMID 35970913, 2022). "The METTL3 level is highly elevated in GSCs and is required for the maintenance of GSCs and the dedifferentiation of glioma cells through an m6A modification in the 3′ UTR of sex-determining region Y (SRY)-Box 2 (SOX2) mRNA93." (PMID 36446846, 2022). "Briefly, this study demonstrates that both HIF1α and HIF2α, as genes upstream of Sox2, regulate the malignant progression of glioma through dedifferentiation." (PMID 34976166, 2022). "ELF4 has been reported to be highly expressed in glioma and can upregulate SOX2 expression to promote stemness." (PMID 35965522, 2022). "It is known that the overexpression of transcription factor SOX2 has been found in different human cancers, including glioma." (PMID 36231068, 2022). "The expression of the neural stem cell markers Nestin and Sox2 are consistent with the features of most drug-resistant glioma stem cell populations and support the neural stem cell lineage of GBM." (PMID 36316307, 2022). "The study confirmed that METTL3 facilitates mRNA methylation, increases the stability of SRY transcription factor 2 (SOX2), improves SOX2 protein expression, and contributes to the radiation resistance and maintenance of glioma stem cell-like cells." (PMID 35711459, 2022). "Previous experiments of our group in mouse high-grade gliomas identified a network of critical tumor-suppressive Sox2 targets, whose inhibition is involved in glioma CSC maintenance, therefore defining new therapeutic targets." (PMID 36232992, 2022). "CBD also led to a downregulation of the sex-determining region Y (SRY)-Box 2 (Sox-2), a critical determinant of glioma tumour initiating cell growth and downstream target of Id-1, in glioblastoma cells." (PMID 35277658, 2022). "For example, METTL3 plays essential roles in preserving glioma stem-like cells and radio-resistance by stabilizing the mRNA of m6A-modified SOX2 via HuR." (PMID 36614956, 2022). "We knocked out HIF1α, HIF2α and Sox2 in glioma cells and cultured them under hypoxic conditions to detect CD133 and CD15 expression." (PMID 34976166, 2022). "Sox2 was also highly expressed in glioma, and there was a positive correlation between the HIF1α/HIF2α and Sox2 expression levels." (PMID 34976166, 2022). "As discussed in a previous paragraph, the transcription factors Sox2 and Oct4 are activated in GSCs promoting glioma cell stemness and stimulating several mechanisms leading to innate and adaptive immune response inhibition." (PMID 35311140, 2022). "Based on our results, we conclude that the dedifferentiation process is induced under hypoxic conditions via regulation by the HIF1α/HIF2α-Sox2 pathway, which provides new ideal targets for glioma treatment." (PMID 34976166, 2022). "The nuclear transcription factor Sox2 is expressed during mammalian embryogenesis in neural progenitor cells and is overexpressed in a variety of tumors, including all grades of gliomas." (PMID 35183162, 2022). "Then, we quantified the expression of lncRNA FOXD2‐AS1, TATA‐box binding protein associated factor 1 (TAF‐1) and NOTCH1 in glioma tissues and GSCs, as well as the expression of GSC stem markers, OCT4, SOX2, Nanog, Nestin and CD133 in GSCs." (PMID 35419917, 2022). "Here, we performed single-nucleus transcriptomics of mutant and wild-type glioma samples sorted for Sox2 stem cell marker." (PMID 36348001, 2022). "we performed the co-expression analysis and confirmed that CAPG2 positively correlates with the expressions of well-defined glioma stem cell marker genes, including Sox2, CD44, MYC and CCND1." (PMID 35898895, 2022).
glioma (continued). "Based on the patient-derived glioma stem cells (GSCs) model, the transcription factor (SOX2)-oncomiR (miR-10b-5p)-TET2 axis was identified, which plays an important role in promoting GBM oncogenesis." (PMID 35494033, 2022). "For example, METTL3 regulates SOX2 mRNA in glioma stem cell maintenance and colorectal tumor progression, LEF1 in osteosarcoma progression, AFF4/NF-kB/MYC in bladder cancer, and SPHK2 in gastric cancer." (PMID 36183833, 2022). "ANGPTL4 overexpression can induce the GSCs enrichment, which is characterized by the expression of polycomb complex proteins BMI-1 and SOX2, contributing to the resistance of glioma cells to temozolomide." (PMID 36247876, 2022). "Overexpression of miR-21 is also related to the upmodulated Sox2 (SRY-Box transcription factor 2), and Sox2 downmodulation can inhibit miR-21-enhanced glioma cell migration and invasion." (PMID 35922753, 2022). "CD133, Nestin and SOX2 expression were positively associated with ITGB8 expression in TCGA and Chinese Glioma Genome Atlas (CGGA) databases, and we further confirmed that ITGB8 was closely correlated with Nestin expression in GBM specimens." (PMID 35676251, 2022). "We addressed this question and performed a series of studies to verify that both HIF1α and HIF2α regulate glioma cell dedifferentiation in a hypoxic microenvironment through Sox2." (PMID 34976166, 2022). "Together with Sox2 they are expressed in nearly all gliomas and their expression rate increases with tumor grade." (PMID 35183162, 2022). "Meanwhile, Sox2 has been multiply shown to be critical in glioma relapse and therapeutic resistance." (PMID 36348001, 2022). "In conclusion, lncPVT1 facilitates stemness and TMZ resistance through regulating miR-365/ELF4/SOX2 signal axis in glioma." (PMID 35965522, 2022). "It was observed that NS formation is accompanied by the activation of five common gliomas of TFs, SOX2, UBTF, NFE2L2, TCF3 and STAT3." (PMID 36231068, 2022). "Among the oncogenic TFs, SOX2 is of particular importance because it is necessary for the CSCs of most gliomas; it is mostly silenced in differentiated cells and operates as a super pioneer TF." (PMID 35921410, 2022). "MALAT1 also acts as a tumor promoter, enhancing the tumorigenesis of glioma stem cells via modulation of miR-129 and subsequent suppression of SOX2." (PMID 33980320, 2021). "Since the association of p21CIP1 and p27KIP1 partly mediates the effect of SRR2 on SOX2 repression in several cell types, we studied the expression of p21CIP1 and p27KIP1 in glioma cell lines and biopsies." (PMID 33805518, 2021). "To verify our data in vivo, we examined glioma tissues from patients and found elevated SOX2 and Nestin expression in high-grade malignant glioma tissues." (PMID 33408794, 2021). "Focusing on samples that harbor focal amplifications of SOX2 (amplitude log 2 (copy number/2) > 0.1), which corresponds to 9% of squamous cancers and 4% of gliomas, we profiled the averaged copy number amplitude surrounding the SOX2 locus." (PMID 34880227, 2021). "We also show the expected DNA damage response of transformed glioma cells to etoposide treatment using double immunofluorescence staining of slice cultures with γH2AX and SOX2." (PMID 33975634, 2021). "Together, these results suggested that 3D collagen I/FN gel promotes glioma growth via the integrin αvβ3/PI3K/AKT/SOX2 signaling pathway." (PMID 33408794, 2021). "Glioma cell lines cultured under stem cell media grow as oncospheres, which express a striking elevation of SOX2 levels." (PMID 33805518, 2021). "The expression of Nestin was upregulated in SOX2 knockdown glioma cells, sand, conversely, SOX2 was upregulated in Nestin knockdown glioma cells." (PMID 33408794, 2021). "In our experiment, NC showed a good inhibitory effect on the self‐renewal ability of glioma stem‐like cells in vitro and also reduced the expression of cancer stem cell markers Oct4, Sox2, and Bim1." (PMID 33788424, 2021).